TFPI (tissue factor pathway inhibitor)
Diseases named in the same sentence as TFPI in open-access papers (continued):
Sharing a sentence is not in itself a finding about the gene and the disease.
Sepsis (continued). "The three major natural anticoagulants (Tissue Factor Pathway Inhibitor (TFPI), Antithrombin (AT), Protein C/S) have been investigated in clinical trials in patients with severe sepsis, with varying success." (PMID 19922636, 2009). "In the study presented here, levels of TFPI remained consistently higher within the first 4 days but were comparable with levels measured on day 5 with sepsis patients without overt DIC." (PMID 39624584, 2024). "At first glance, this seems to contradict the conclusions drawn from previous smaller studies that confirmed the assumption that TF is not balanced by TFPI in sepsis." (PMID 38914630, 2024). "In sepsis-induced DIC, tissue factor (TF) and factor VIIa pathway mainly activate coagulation cascade and increase TF expression compared to tissue factor pathway inhibitor (TFPI)." (PMID 34513536, 2021). "The OPTIMIST trial, investigating rh-TFPI in sepsis patients, suggested a protective effect from rh-TFPI in a subgroup of CAP patients, especially when not treated with heparin." (PMID 25992779, 2015). "There were no statistical differences in the TFPI levels among the healthy control, sepsis and severe sepsis groups (P > 0.05)." (PMID 26025445, 2015). "Neither infusion of antithrombin (AT) nor infusion of rh-tissue factor pathway inhibitor (TFPI) has been found to improve outcome in sepsis." (PMID 22546487, 2012). "This study could not detect an effect of recombinant TFPI (i.e. Tifacogin) on mortality in the primary study population, i.e. patients with severe sepsis and international normalized ratio (INR) ≥ 1.2, but an increased rate of bleeding." (PMID 38914630, 2024). "Attempts to attenuate coagulation activation with an inhibitor of tissue factor (TF), i.e. tissue factor pathway inhibitor (TFPI), revealed no survival benefit in a heterogenous group of sepsis patients, but a potential survival benefit in patients with an international normalized ratio (INR) < 1.2." (PMID 38914630, 2024). "In addition to FDA-approved drugs, a variety of currently non-FDA-approved agents, including recombinant TM, APC, and TFPI, have been evaluated in sepsis." (PMID 37081895, 2023). "There are also many alternative compounds to rhAPC that are currently in Phase III clinical trials which include TFPI, TNF-antibody fragment, antithrombin III and platelet-activating factor acetylhydrolase, although TFI and antithrombin have been ineffective against severe sepsis and septic shock." (PMID 35186813, 2021). "However, in sepsis, endothelium anticoagulant factors such as TFPI do not operate appropriately, thereby allowing leukocyte and platelet adhesion and, consequently, the release of tissue factor and the formation of microthrombi." (PMID 35052592, 2021). "Restoration of anticoagulant pathways by administration of antithrombin (AT) III, recombinant activated protein C (APC) and recombinant tissue factor pathway inhibitor (TFPI) in patients with sepsis without DIC has not resulted in survival benefits in randomized controlled trials." (PMID 28288667, 2017). "Neither activated protein C nor tissue factor pathway inhibitor (TFPI) seem appropriate for testing in EBOV based on negative RCTs in classical sepsis and concerns that they may exacerbate bleeding." (PMID 26425845, 2015). "However, in our sample the plasma TFPI values among the healthy controls, sepsis and severe sepsis groups were not significantly different." (PMID 26025445, 2015). "Finally, the tissue factor pathway inhibitor (TFPI) inactivates the tissue factor–factor VIIa complex and is produced by several cells, including endothelial cells, but its levels are decreased in sepsis resulting in dysregulated inactivation of the tissue factor–factor VIIa complex." (PMID 36836706, 2023). "Only TFPI levels and TF-PCA discriminated between sepsis patients with or without DIC (area under the curve = 0.76; P = .0002)." (PMID 39624584, 2024).
Sepsis (continued). "In patients with severe sepsis, thrombin generation, APC, TFPI and TM are not the true markers of “DIC”, but are interpreted as secondary markers of TF path." (PMID 31160889, 2019).
thrombosis (30 papers, 2009 to 2025). "In this study, a total of 6 groups were included to analyze the influence of TFPI rs7586970 T/C variation on the risk of venous thrombosis caused by increased plasma TFPI concentrations." (PMID 32897244, 2020). "For instance, in Germany, the polymorphisms of P151L located in TFPI have been put forward in patients with venous thrombosis." (PMID 28716011, 2017). "Low overall plasma levels of TFPI have been associated with recurrent venous thrombosis in the general population." (PMID 27924945, 2016). "Patients with TFPI levels at or less than the 10th percentile of the normal reference range for TFPI are at slightly increased risk for venous thrombosis and coronary heart disease." (PMID 26481314, 2015). "This is of interest since increased TFPI levels have been reported in patients with unstable angina or acute myocardial infarction suggesting a possible causal role in coronary thrombosis." (PMID 21619612, 2011). "In the present study, we assessed total plasma TFPI activity via inhibition of the TF-FVIIa complex, which might explain why TFPI did not mediate, at least in part, the association between apo B and venous thrombosis risk." (PMID 28540474, 2017). "The lower levels of TFPI protein have been associated with increased risk of venous thrombosis." (PMID 25349733, 2014). "Likewise, reduced f-TFPI levels have been recently linked to intravascular thrombosis in patients with a stroke or deep vein thombosis." (PMID 21619612, 2011). "Therefore, TFPI SNV is another genetic risk factor for the development of thrombosis in APS." (PMID 31040845, 2019). "In plasma, decreased in f-TFPI and increased in PAI-1 levels are both associated with the risk of thrombosis." (PMID 33465109, 2021). "Meta-analysis results showed that among 1829 venous thrombosis patients and normal controls, plasma TFPI concentration was significantly reduced in carriers of the rs7586970 T allele (p=0.03, OR=0.87)." (PMID 32897244, 2020). "Our results therefore suggest that the importance of TFPI in regulating coagulation in the laser injury thrombosis model exceeds that of thrombomodulin." (PMID 31351019, 2019). "The absolute number of TFPI+ MPs did not significantly differ between Th+ and Th− BS patients (not shown), but, surprisingly, we found that a significantly lower percentage of MP were TFPI+ in the BS patients with a history of thrombosis (p < 0.05)." (PMID 27924945, 2016). "It would be ideal to conduct a prospective study testing the ability of TF+ and TFPI+ MPs to predict a first thrombosis in BS." (PMID 27924945, 2016). "Additionally, they investigated whether a decreased level of TFPI is a risk factor for the development of deep vein thrombosis (DVT)." (PMID 41303494, 2025). "We demonstrate that endothelial BAMBI influences fibrin generation and thrombus stability by modulating thrombomodulin and TFPI anticoagulant function of the endothelium; we also highlight the importance of these anticoagulant proteins in the laser‐induced thrombosis model." (PMID 31351019, 2019). "As reported in the scientific literature, during arterial thrombosis, procoagulant activity may also be enhanced as a result of an indispensable element of NETs neutrophil elastase, which influences inactivation of the tissue factor pathway inhibitor (TFPI)." (PMID 29404659, 2018). "NE upregulates tissue factor (TF) activity and coagulation by degrading tissue factor pathway inhibitor (TFPI), an endogenous anticoagulant protein leading to arterial thrombosis in infections in vivo." (PMID 36671467, 2022). "Tissue factor pathway inhibitor (TFPI) is a plasma multivalent Kunitz-type serine protease inhibitor that interacts with FV, and this interaction may alter the formation of venous thrombosis and may be related to cancer progression." (PMID 33072582, 2020).
thrombosis (continued). "BD patients who had already presented with thrombosis in the past exhibited elevated counts of total and TF positive microparticles in comparison to individuals without thrombosis, but showed a lower percentage of TFPI positive microparticles." (PMID 31244756, 2019). "NSCLC patients with deep venous thrombosis (DVT) or metastasis had significantly lower TFPI-1 levels than those without DVT or metastasis (P < 0.01, resp)." (PMID 28246607, 2017). "This is supported by Th− patients having a significantly higher TFPI/TF ratio, and indeed by the absence of a thrombosis history in all individuals with a ratio >0.7." (PMID 27924945, 2016). "Strikingly, Th− BS patients without a history of thrombosis had a higher median TFPI/TF MP ratio compared with Th+ patients (0.72 vs. 0.23; p < 0.0001), with no patient with a ratio of >0.7 having a history of a thrombotic event." (PMID 27924945, 2016). "As NETs probably hold prothrombotic properties like platelet activation, coagulation activation by factor XII and tissue factor, tissue factor pathway inhibitor (TFPI) suppression and inhibition of fibrinolysis, a role in coronary thrombosis would be plausible." (PMID 28074081, 2016). "On this background, it was particularly interesting that BS patients with a history of thrombosis had a significantly lower proportion of TFPI+ MP compared to those without." (PMID 27924945, 2016). "TFPI has not been demonstrated to be efficacious for the prevention of deep venous thrombosis in critically ill patients." (PMID 19284881, 2009). "The LA induced increase in coagulation factor III (CFIII), fibrinogen, plasminogen activation inhibitor-1 (PAI-1), TFPI and soluble PECAM-1/CD31 levels are also noted in severe COVID-19 associated thrombosis as are the thrombocytopenia and an elevated activated clotting time." (PMID 35502320, 2022). "Furthermore, discrimination between patients with and without a history of clinically overt thrombosis was improved by factoring in the level of MP expressing TFPI." (PMID 27924945, 2016).
breast carcinoma (29 papers, 2007 to 2025). "Tissue factor pathway inhibitor (TFPI) has been shown to be associated with breast cancer pathogenesis." (PMID 26999742, 2016). "Knock down of syndecan-3 in endothelial,- smooth muscle- and breast cancer cells reduced the TFPI surface levels by 20-50%, and an association of TFPIα to syndecan-3 on the cell surface was demonstrated." (PMID 25617766, 2015). "Survival data were not available for our patient cohort, however, access to a merged breast cancer dataset from GOBO allowed us to investigate possible associations between TFPI or TF gene expression and outcome." (PMID 25882602, 2015). "The clinical relevance of expression and genetic variants of TFPI in breast cancer appeared distinct from that of TF." (PMID 25882602, 2015). "Sex bias in single-nucleotide polymorphism (SNP) has also been reported recently for tissue factor (TF) and TF pathway inhibitor (TFPI) genes among patients with coronary heart disease and type-2 diabetes and the risk of breast cancer in men." (PMID 23503716, 2013). "To explore the potential anticoagulant activity of the breast cancer and endothelial cell-associated TFPI, we measured the TF activity on the Sum102, MDA-MB-231 and HCAEC cell surface indirectly by a chromogenic FXa activity assay." (PMID 23320987, 2013). "Overexpression of either isoform of TFPI resulted in expression profiles that associated significantly with tumor grade and ER status in a breast cancer patient material." (PMID 23071754, 2012). "The association between TFPI and ER status is also intriguing as anti-estrogen therapy is important in breast cancer treatment." (PMID 23071754, 2012). "The inter-relationships between TFPI and TF tagSNPs, tumor mRNA expression and plasma levels, and their association with breast cancer subtypes and survival were explored in either 152 treatment naive breast cancer patients or a merged 1881-sample breast tumor data set." (PMID 25882602, 2015). "In the present case-control study, we aimed to investigate the role of common single nucleotide polymorphisms (SNPs) in genes involved in the TF pathway of coagulation (i.e., the F2, F3 (TF) F5, F7, F10, EPCR, and TFPI genes) on the susceptibility of breast cancer." (PMID 25407022, 2014). "Moreover, the expression of TF associated with TFPI expression in all breast cancer cell lines tested except the Sum149 cells." (PMID 23320987, 2013). "Similar complex features of the two isoforms of TFPI were observed in breast cancer cells and in endothelial cells, although the variation in TFPI levels in the different breast cancer cell lines demonstrated a tumor-associated regulative control of the endogenous TFPI expression." (PMID 23320987, 2013). "TFPI was observed to induce invasive tumor growth upon silencing in breast cancer cells, while its overexpression triggered apoptosis." (PMID 38576019, 2024). "It was reported that the downregulation of TFPI decreased the apoptosis in breast cancer cells, but ectopic overexpression of TFPI increased apoptosis." (PMID 36900315, 2023). "The TFPI is an endogenous inhibitor of TF-induced coagulation, and it has been shown to be expressed by numerous breast cancer cell lines." (PMID 36980680, 2023). "The expression level of TFPI in luminal-A breast cancer patients was significantly lower than that in healthy volunteers." (PMID 34115774, 2021). "Our results indicate that ERα can interact with all three ERE half-sites in the TFPI 5’-flanking region and thus participate in the repression of oestrogen mediated TFPI transcription in breast cancer cells." (PMID 26999742, 2016). "Recently, we found TFPI mRNA levels to be significantly reduced by oestrogens in a breast cancer cell line (MCF7), a process mediated through the oestrogen receptor alpha (ERα)." (PMID 26999742, 2016).
breast carcinoma (continued). "TFPI is mainly synthesized by endothelial cells, however, its expression has been detected in many cancer cells, in particular breast cancer cell lines and circumstantial evidence suggests that it possesses anti-cancer properties." (PMID 26999742, 2016). "In a recent report, we demonstrated that oestrogens downregulated TFPI mRNA and protein levels in the ERα expressing breast cancer cell line MCF7." (PMID 26999742, 2016). "Here, we aimed to investigate the clinical relevance of TF and TFPI genetic and phenotypic diversity in breast cancer." (PMID 25882602, 2015). "Expression of both TF and TFPI has been detected in tissues and cell lines of several human cancers including breast cancer, suggesting a role in cancer biology." (PMID 25882602, 2015). "Because survival data were not available for the patients included in our study, we made use of a merged clinical dataset to investigate the effect of TFPI and TF tumor expression on survival among breast cancer patients." (PMID 25882602, 2015). "In the present study, we aimed to investigate the clinical relevance of TFPI and TF in breast cancer." (PMID 25882602, 2015). "This was performed by evaluating the expression of syndecans 1–4 and the binding potential of endogenously expressed TFPI to syndecans on the cell surface of primary human endothelial- and smooth muscle cells, and basal breast cancer cells." (PMID 25617766, 2015). "Glypican 3 knock down did not alter the cell surface TFPI levels in Sum102, thus demonstrating glypican 3 as an unlikely binding molecule for TFPI in these breast cancer cells." (PMID 25617766, 2015). "We selected endothelial-, smooth muscle-, and breast cancer cells with high endogenous TFPI expression for investigation." (PMID 25617766, 2015). "We evaluated the adhesion of breast cancer cells to immobilized TFPI under static and shear conditions (0.35 – 1.3 dyn/cm2)." (PMID 25849335, 2015). "Here we provide results suggesting that TFPI represents a promising marker of breast cancer progression and prognosis." (PMID 25882602, 2015). "Our findings indicate a possible functional implication of TFPIβ in locally reducing TF signaling and breast cancer cell progression, further endorsing involvement of TFPI in malignant disease." (PMID 23320987, 2013). "The relative mRNA ratios between the two TFPI isoforms correlated well in all the breast cancer cell lines in terms of TFPIα being the major isoform, which is consistent with our findings and previous results in endothelial cells." (PMID 23320987, 2013). "Tissue factor (TF) pathway inhibitor-1 (TFPI) is expressed in several malignant tissues- and cell lines and we recently reported that it possesses anti-tumor effects in breast cancer cells, indicating a biological role of TFPI in cancer." (PMID 23320987, 2013). "We report here considerable variations in the expression of both TFPI isoforms among the various breast cancer cell lines tested." (PMID 23320987, 2013). "When looking further into the characteristics of the different breast cancer cell lines, we discovered a similar substantial variation in the TF mRNA expression as observed for TFPI." (PMID 23320987, 2013). "The GPI-attached, cell bound TFPI was found to be functionally active, and to our knowledge, demonstrating for the first time anticoagulant properties of TFPI expressed on the surface of breast cancer cells." (PMID 23320987, 2013). "Since the endothelium is considered to be the predominant site of TFPI synthesis, the TFPI characteristics of the breast cancer cells were compared to normal endothelial cells." (PMID 23320987, 2013). "The TFPI characteristics in the breast cancer cell lines were very similar to those observed in the primary endothelial cells HCAEC." (PMID 23320987, 2013). "We provide evidence for the expression of both isoforms of TFPI (TFPIα and TFPIβ) in tumor derived breast cancer cell lines." (PMID 23320987, 2013).